MUC5AC (mucin 5AC, oligomeric mucus/gel-forming)
Diseases named in the same sentence as MUC5AC in open-access papers (continued):
Sharing a sentence is not in itself a finding about the gene and the disease.
asthma (continued). "Herein, we review our current understanding of the role of MUC5AC and MUC5B in mucus dysfunction in asthma." (PMID 29186064, 2017). "Altered MUC5AC and MUC5B gene expression is consistently observed in both asthma models and individuals with disease." (PMID 29186064, 2017). "In control subjects and children with stable asthma, the geometric means of the MUC5B:MUC5AC ratios were 31.6 and 9.33, respectively (P = .119), and the mean difference was 3.37 (95% CI, 0.71-15.92)." (PMID 28716644, 2017). "Individuals with type 2 high asthma also have elevated levels of MUC5AC compared with healthy controls or individuals with type 2 low asthma; a substantial decrease in MUC5B expression is also observed in type 2 high asthma." (PMID 29186064, 2017). "MUC5AC protein was detected in airway epithelia, and MUC5AC expression mostly coincided with the expression of CLCA1, as previously reported in asthma." (PMID 22731784, 2012). "Additionally, the induction of MUC5AC and MUC2 and the repression of MUC5B were seen, which are specific to Th2-high asthma." (PMID 41303221, 2025). "Our findings of higher numbers of MUC5AC-positive goblet cells in mucus-plugged airways confirmed and extended prior findings of MUC5AC overexpression in the airways in fatal and nonfatal asthma." (PMID 40091838, 2025). "We found that mucus plugs from patients with asthma were rich in MUC5AC, whereas those from patients with COPD were rich in MUC5B, and the ratio of MUC5AC to MUC5B was significantly higher in asthma than in COPD." (PMID 40091838, 2025). "However, in the presence of IL-13 activation as a model of severe asthma, MTOR signaling was required for key features of airway mucous cell metaplasia, MUC5AC staining levels, and number of eGC." (PMID 40446022, 2025). "The granulocytic plugs in nonfatal asthma were characterized by a balanced mixture of MUC5AC and MUC5B mucins and the presence of extracellular DNA traps." (PMID 40091838, 2025). "The relative lack of granulocytes in many of the fatal asthma mucus plugs reported here indicates that these plugs can form without granulocyte assistance, perhaps as a result of very high MUC5AC protein levels that can self-form mucus plugs." (PMID 40091838, 2025). "We identified a potential five-biomarker panel (BPIFA1, MUC5AC, CAMP, CTSG, and ANXA1) that illustrates the inflammatory activity of asthma in sputum and could improve asthma phenotyping, providing valuable insights into personalized treatment approaches." (PMID 38542471, 2024). "Two mucins, MUC5AC and MUC5B, were reported to be the most involved in asthma pathogenesis." (PMID 38259471, 2023). "Additionally, Peroxisome proliferator-activated receptor (PPAR) signaling pathway up-regulates the expression of Muc5ac in airway epithelial cells and ST2 expression in Th2 cells, both of which critically contribute to asthma pathogenesis." (PMID 37377967, 2023). "MUC5AC has been used as a marker of goblet cell metaplasia and is upregulated in various chronic respiratory inflammatory disorders, such as COPD, CF, and asthma." (PMID 37762530, 2023). "In our HDM-induced asthma model, we found that PEP-NASP peptide treatment markedly ameliorated AHR and reduced the production of type two inflammatory cytokines (IL-5 and IL-13) and MUC5AC." (PMID 36012669, 2022). "Therefore, we focused on the overexpression of the MUC5AC genes and the related signaling pathways induced by HDM extracts in bronchial epithelial cells and an HDM-induced asthma animal model." (PMID 36012669, 2022). "In this study, we investigated the protective effect of BV extract—which has been clinically applied, rather than its components —on mucus metaplasia in asthma, assessing the effect of BV on IL-13-mediated STAT6 activation and MUC5AC production in the human airway epithelial cell line A549." (PMID 34822557, 2021).
asthma (continued). "They observed that infant mice exposed to PM+HDM failed to develop a typical asthma phenotype including airway hyperresponsiveness, Th2 inflammation, Muc5ac expression, eosinophilia, and HDM-specific Ig compared to only HDM-exposed mice." (PMID 32411804, 2020). "We found high levels of MUC5AC mRNA in patients with severe asthma but did not identify any differential expression of KIAA1109 in the same bronchial epithelial datasets." (PMID 30552067, 2019). "To determine the contribution of TGF-β3 in induction of ROS and autophagy and MUC5AC expression in asthma mice models, we examined the effects of a TGF-β3-neutralizing antibody on ROS generation, autophagy activation, and MUC5AC expression of mice after the seventh HDM challenge." (PMID 32082074, 2019). "We found MUC5AC and KIAA1109 expression is present in airway epithelium and localised to the cytoplasm and membrane; therefore, we hypothesised that concentrations of MUC5AC and KIAA1109 could be altered in airway epithelium in patients with severe asthma." (PMID 30552067, 2019). "We also demonstrated that MUC5AC and MUC5B form distinct extracellular domains and that IL-13 induces a heterogeneous gel, which could have implications for mucociliary clearance in asthma." (PMID 29186064, 2017). "Increased MUC5AC and MUC5B protein have been reported in sputum from individuals with asthma." (PMID 29186064, 2017). "Our data indicate that the features of these asthma models that were significantly influenced by TNFRSF14 include blood levels of Ag-specific IgE, airway inflammation, AHR, lung collagen content and airway goblet cell hyperplasia and BAL Muc5AC content." (PMID 27982078, 2016). "We found that non-asthma smoker donor 23 had three fold higher basal expression level of MUC5AC, whereas non-asthma smoker donor 11 had an expression level of MUC5AC similar to other non-asthma non-smoker donors." (PMID 25706956, 2015). "Removal of non-asthma smokers (donors 11 and 23) from the data set resulted in significant responses of MUC5AC expression after RV-A16 infection in both non-asthma donors (p = 0.01) and asthma donors (p = 0.0001)." (PMID 25706956, 2015). "Contrasting with the effects on lines of asthma phenotypes, CD86 siRNA treatment failed to ameliorate the goblet cell hyperplasia and MUC5AC gene expression, cardinal features of airway remodeling in asthma." (PMID 25344652, 2014). "Comparison of the expression patterns of MUC5AC-core genes between asthma patients at baseline and healthy nonsmokers demonstrated that 6 of the 73 (8%) MUC5AC-core genes were up-regulated and 1 MUC5AC-core gene was down-regulated in asthma." (PMID 22676183, 2012). "The present study adds to an accumulating body of evidence from gene-array studies that genes such as CLCA1, SerpineB2, MUC5AC, AGR2, CPA3, and tryptase are overexpressed in asthma, and suggests that these genes are more transcriptionally active in the EIB phenotype." (PMID 20052409, 2010). "In human, it has been reported that MUC5AC expression, measured using real-time RT-PCR, is much higher than both MUC5B and MUC4 in homogenates of endobronchial biopsies from healthy subjects or subjects with asthma." (PMID 17550583, 2007). "Using a metric of mucus tethering (percentage tethering) to quantify the degree of continuity between the mucus plugs and the epithelium, we found that percentage of tethering correlated positively and significantly with MUC5AC immunostaining in asthma but not in COPD." (PMID 40091838, 2025). "Similarly, airway epithelial cells from patients with asthma and COPD have higher expression levels of MUC5AC than those from healthy individuals, so screens to identify compounds to reduce goblet cell metaplasia or mucous hypersecretion would also be feasible in disease contexts." (PMID 39137525, 2024).
asthma (continued). "Indeed, in healthy airways and bronchioles there was little to no Muc5ac (a pathological mucin highly upregulated in asthma) expression in the epithelial monolayer, nor immune cell infiltrate near airways in the surrounding alveolar space." (PMID 37928904, 2023). "Previous studies have found that IL-13 could contribute to the promotion of goblet cell proliferation, and IL-13 knockout mice with asthma do not exhibit promoted goblet cell hyperplasia in the airways or Muc5AC expression in lung tissue." (PMID 29962952, 2018). "However, changes in the relative proportion of MUC5AC and MUC5B are observed in asthma." (PMID 29186064, 2017). "One randomized controlled trial reported that MUC5AC expression was downregulated in patients with both CRSwNP and aspirin-resistant asthma after 2 weeks of oral prednisone therapy followed by 12 weeks of intranasal corticosteroids but not in patients with both CRSwNP and aspirin-intolerant asthma." (PMID 37762530, 2023). "In vivo, daily treatment with budesonide did not modify MUC5AC and MUC5B expression in bronchial biopsies from patients with mild asthma." (PMID 34248677, 2021). "MUC5B, ORMDL3, MUC5AC, CHI3L1, CLCA1, and IL-33 displayed a high non-specific relationship with allergic and nonallergic asthma." (PMID 33936056, 2021). "There are currently no studies available that provide information regarding the role of NKB in regulating muc5AC or muc5B expression, nor of SubP or NKA in the regulation of muc5B, in asthma." (PMID 30081920, 2018). "Several studies have compared the size distribution of MUC5AC and MUC5B in sputum from patients with asthma, yet no discernible difference has been observed." (PMID 29186064, 2017). "Jinnai et al9 reported an association between airway eosinophils and total mucin concentration in the sputum of adults with stable asthma; they did not distinguish between MUC5B or MUC5AC." (PMID 28716644, 2017).
pancreatic cancer (58 papers, 2004 to 2025). "Among the mucins, expression of MUC5AC is associated with PanINs and all stages of pancreatic cancer, and a low frequency of MUC2 expression is associated with cystic lesions." (PMID 33915081, 2021). "Of these proteins, the levels of pancreatic cancer-associated proteins, such as MUC5AC, MUC2, and CEA, were high." (PMID 32842508, 2020). "Overexpression of MUC5AC has been associated with poor prognosis of lung cancer, cholangiocarcinoma and pancreatic cancer." (PMID 24722639, 2014). "The present work is the first demonstration of an association of MUC5AC with pancreatic cancer cell invasion." (PMID 20492722, 2010). "Thus, preliminary studies were conducted to transfect the human CFPAC pancreatic cancer cell line with a plasmid encoding the peptide M-MUC5AC-CH-long, from the C-terminal region of MUC5AC." (PMID 24257318, 2013). "Although we showed no direct evidence that MUC5AC was associated with tumorigenesis of pancreatic tumor, it was likely that inhibition of MUC5AC might reduce VEGF production by tumor in vivo." (PMID 20492722, 2010). "Preclinical and clinical studies have established MUC5AC’s role in conferring aggressive features to pancreatic cancer cells, including viability, anchorage-independent growth, motility, adhesion, angiogenesis, invasion, metastasis, and chemoresistance." (PMID 40260290, 2025). "GEM treatment induces MUC5AC overexpression in pancreatic cancer, disrupting E-cadherin/β-catenin junctions and promoting β-catenin nuclear translocation, which increases MYC expression." (PMID 39990228, 2025). "MUC5AC has been investigated in PC detection in blood with 174.6 ng/mL in early pancreatic cancer and 228.7 ng/mL in late pancreatic cancer." (PMID 40363817, 2025). "Based on our observations from these preliminary data, we postulate that MUC5AC plays a central role in driving the aggressiveness of pancreatic tumor cells, with circulating sMUC5AC levels reflecting its activity at a given time point." (PMID 40260290, 2025). "Different tumor-specific antibodies conjugated to fluorophores, including anti-CEA, anti-CA19.9, and anti-MUC5AC, have been used to target pancreatic cancer in orthotopic mouse models." (PMID 39458160, 2024). "When subjected to growth factors, pancreatic cancer cell lines (PCLs) produced more mature than immature MUC5AC isoforms, indicating the difference in their function and malignant potential." (PMID 37175794, 2023). "The present study reports the use of fluorescent anti-MUC5AC antibody to selectively and brightly label a liver metastasis of pancreatic cancer in a patient-derived orthotopic xenograft (PDOX) mouse model." (PMID 37241027, 2023). "This warrants close examination of the pancreatic tumor microenvironment that plays a role in MUC5AC production or upregulation." (PMID 37175794, 2023). "At a threshold of 96% specificity, 78% and 83% of pancreatic cancer patients showed increased expression of CA19-9 in MUC5AC and MUC1, respectively." (PMID 37455827, 2023). "This study proved MUC5AC’s role in the pancreatic cancer cell, including viability, anchorage-independent growth, motility, adhesion to the extracellular matrix, angiogenesis, apoptosis, and sensitivity to gemcitabine." (PMID 37175794, 2023). "Coadministration of a glutaminase inhibitor with gemcitabine also abrogated MUC5AC (Mucin 5AC)-mediated gemcitabine resistance in mouse and human pancreatic cancers, providing a new target for future immunotherapy." (PMID 35515122, 2022). "If the same criteria are applied to our study, MUC5AC ispositive in at least 55% of all pancreatic cancers, suggesting that this tumor typemay be an ideal application for new drugs specifically targeting MUC5AC." (PMID 35764407, 2022). "Several studies revealed that secreted MUC5AC is overexpressed in pancreatic cancer, lung cancer, and breast cancer." (PMID 36618366, 2022).
pancreatic cancer (continued). "Mucin 5AC (MUC5AC) is of particular interest in pancreatic cancer as it is aberrantlyexpressed in a large fraction of these cancers." (PMID 35764407, 2022). "Researchers in the University of Nebraska Medical Center recently found that MUC5AC, as a link between β-catenin and c-Myc, increased glutamine uptake, which was used in pancreatic cancer cells." (PMID 35709153, 2022). "Here, we shed light on the available evidence on mucin, MUC5AC in predicting the outcome of pancreatic cancers." (PMID 34205412, 2021). "More clinical and pre-clinical studies are required to understand the impact of MUC5AC on the outcomes of pancreatic cancers." (PMID 34205412, 2021). "In a phase I study of pancreatic cancer patients preselected for MUC5AC expression, a favorable toxicity profile was found for Ensituximab." (PMID 33373033, 2021). "The PAM4 mAb, which recognizes a carbohydrate-induced conformational epitope on MUC1 and MUC5AC, has been evaluated as a targeting vehicle for therapy and imaging of pancreatic cancer." (PMID 33371487, 2020). "To select suitable pancreatic cancer cells for the assay, we analyzed the expression of genes B3GNT6 (encoding β3Gn-T6) and MUC5AC, together with genes encoding core 2 synthases (GCNT1, GCNT3, and GCNT4) by qRT-PCR." (PMID 33253272, 2020). "Altered N-glycosylation in pancreatic cancer tissue compared to normal pancreatic tissue was reported for MUC5AC, LGALS3BP, CEACAM5, and IGFBP3." (PMID 30771135, 2019). "There is increasing evidence between aberrant glycosylations or expression of mucin peptides and neoplasms, such as MUC1, MUC2, MUC5AC in pancreatic neoplasm; MUC1, MUC4 in Gastrointestinal neoplasms." (PMID 27374181, 2016). "On the other hand, MUC5AC is generally undetectable in normal pancreas tissue and is sometimes ectopically induced in pancreatic tumor cells." (PMID 25166306, 2014). "In this study, we have demonstrated that suppression of MUC5AC which was commonly expressed in pancreatic ductal carcinoma reduced adhesive, invasive and metastatic potential of pancreatic cancer cell lines." (PMID 20492722, 2010). "Recently, methylated CpG mapping of MUC2 and MUC5AC promoters have been determined in pancreatic cancer cell lines." (PMID 24281201, 2010). "We down-regulated MUC5AC expression by siRNA and investigated the effects on the malignant and metastatic potential of human pancreatic cancer cell lines, SW1990 and BxPC3." (PMID 20492722, 2010). "Small-interfering (si) RNA directed against MUC5AC were used to assess the effects of MUC5AC on invasion and adhesion of pancreas cancer cells in vitro and in vivo." (PMID 20492722, 2010). "Transcriptional activity of the MUC5AC promoter region was analyzed in pancreatic cancer cell lines, SW1990 and HPAF." (PMID 24281201, 2010). "Here, we report the impact of MUC5AC on the adhesive and invasive ability of pancreatic cancer cells." (PMID 20492722, 2010). "In blood tests, MUC5AC has been detected in colon and pancreas cancer." (PMID 40363817, 2025). "Enhancement of the visualization of pancreatic ductal adenocarcinoma (PDAC) tumor margins using near-infrared dye-conjugated tumor-specific antibodies was pioneered by using anti-CEA, anti-CA19.9, and anti-MUC5AC in orthotopic mouse models of pancreatic cancer." (PMID 39458160, 2024). "Secreted mucin 5AC (MUC5AC), a marker for early pancreatic neoplasia, regulates the development of pancreatic cancer and promotes the expression of cancer stem cell markers in an autochthonous murine model of pancreatic cancer (Pdx-1cre, KrasG12D)." (PMID 37239940, 2023). "Therefore, an anti-MUC5AC fluorescent antibody is an excellent candidate for targeting metastatic pancreatic tumor deposits in the abdomen." (PMID 37241027, 2023). "Prognostic impact of MUC5AC in pancreatic cancer is unclear with mixed outcomes." (PMID 36672382, 2023).